SNAP29 (synaptosome associated protein 29)
Diseases named in the same sentence as SNAP29 in open-access papers (continued):
Sharing a sentence is not in itself a finding about the gene and the disease.
Cognitive impairment (1 paper, 2021). Abnormal cognition is characterized by deficits in thinking, reasoning, or remembering. "Since we found that long-range neural projections were impaired after SNAP29 knockdown in the hippocampus, we subsequently asked whether SNAP29 reduction was sufficient to cause cognitive impairment in mice." (PMID 33754017, 2021). "Further, SNAP29 reduction emerged as a causative factor of cognitive impairment." (PMID 33754017, 2021). "Although we found that ischemia-induced SNAP29 reduction was closely associated with poststroke cognitive impairment, there is still a lack of information regarding SNAP29 protein levels in other neurodegenerative diseases." (PMID 33754017, 2021). "So, strategies to maintain the function of SNAP29 may be vital for mitigating poststroke cognitive impairment." (PMID 33754017, 2021).
COVID-19 (1 paper, 2021). A disease caused by infection with severe acute respiratory syndrome coronavirus 2. "Specifically, SARS-CoV-2 infection was shown to block autophagic flux by elevating GSK3β expression in lung cancer lines, or by depleting autophagy genes, such as SNAP29 (Synaptosomal-Associated Protein 29) along with lysosomal acidification genes in COVID-19 lung biopsy samples." (PMID 34054782, 2021).
Infertility (1 paper, 2019). "We propose that hemizygosity for SNAP29 maybe the underlying cause for male associated infertility in 22q11.2DS." (PMID 31633066, 2019).
Intellectual disability (1 paper, 2015). "For example, in the context of identifying novel intellectual disability candidate genes in a large-scale screening study, flies with a knockdown of SNAP29 were found to have profound synaptic defects characterized by abnormal basal neurotransmission." (PMID 26137170, 2015).
ischemia (1 paper, 2021). A hypoperfusion of the BLOOD through an organ or tissue caused by a PATHOLOGIC CONSTRICTION or obstruction of its BLOOD VESSELS, or an absence of BLOOD CIRCULATION. "The differentially expressed synaptosome associated protein 29 (SNAP29)-interacting proteins upon ischemia and reperfusion were analyzed with bioinformatics analysis and the results indicated that the changes of SNAP29 after acute ischemia were mainly involved in the synaptic functions." (PMID 33754017, 2021). "In this study, the expression level of SNAP29 decreased after acute ischemia and this reduction was significant in neurons." (PMID 33754017, 2021). "The outcomes of SNAP29 reduction were assessed with SNAP29 knockdown, which mimicked the distribution of SNAP29 along neuronal processes after acute ischemia." (PMID 33754017, 2021). "Notably, the reduction in SNAP29 did not influence autophagic flux, but did influence synaptic transmission efficiency following acute ischemia and during subsequent reperfusion." (PMID 33754017, 2021).
Legionella infection (1 paper, 2025). "In cells expressing the PR-Ub deficient mutant of SNAP29, SNAP29 forms puncta upon both WT and ΔS Legionella infection; some of which colocalize with bacteria." (PMID 40506485, 2025). "In WT Legionella infection or in SdeA-expressing cells both STX17 and SNAP29 are modified by PR-Ub." (PMID 40506485, 2025).
male infertility (1 paper, 2019). The inability of the male to effect fertilization of an ovum after a specified period of unprotected intercourse. "Thus, we postulate that SNAP29 may also be required during sperm maturation, since only 10% of seminiferous tubules of Snap29−/− mutant males were abnormal and this alone cannot explain the observed male infertility." (PMID 31633066, 2019).
MRKH syndrome (1 paper, 2021). "Genes other than TBX1 could be involved in the development of uterine malformations described in MRKH syndrome, such as SNAP29, or other genes in the same genetic pathway as TBX1." (PMID 33883018, 2021).
pancreatic cancer (1 paper, 2019). "This along with the previously observed outcomes in pancreatic cancer patients may suggest a more redundant role for SNAP29." (PMID 31712554, 2019).
prostate carcinoma (1 paper, 2023). A carcinoma that arises from epithelial cells of the prostate gland. "These experiments indicate that SNAP29 depletion does not affect secretory autophagy in prostate cancer PC-3 cells." (PMID 37285022, 2023).
renal failure (1 paper, 2021). "SNAP29, another gene associated with kidney defects in the same study, had renal failure, NOS in its top 1% phenome associations." (PMID 34715901, 2021).
Strabismus (1 paper, 2025). A misalignment of the eyes so that the visual axes deviate from bifoveal fixation. "In contrast, features such as strabismus were observed in 67% of patients in the newer cohort (4/6) but only 10.5% in the earlier series (2/19), further supporting its emerging association with SNAP29 mutations." (PMID 40709160, 2025).
Stroke (1 paper, 2021). Sudden impairment of blood flow to a part of the brain due to occlusion or rupture of an artery to the brain. "As SNAP29 is a member of the SNARE complex mediating fusion of autophagosomes and lysosomes, in this study we investigated the protein levels of the SNARE complex and found sustained reduction in SNAP29 after stroke." (PMID 33754017, 2021).
type 1 diabetic (1 paper, 2025). "Moreover, in diabetic cardiomyopathy, O-GlcNAcylation of SNAP29 disrupts the formation of the SNAP29-STX17-VAMP8 complex that mediates autophagosome-lysosome fusion, thereby impairing autophagy-dependent degradation and exacerbating myocardial injury in type 1 diabetic rats." (PMID 41280891, 2025).
infection (10 papers, 2012 to 2025). The state of being infected such as from the introduction of a foreign agent such as serum, vaccine, antigenic substance or organism. "Proteomic analysis has shown that the SNARE proteins Syntaxin17 (STX17) and SNAP29 are PR-ubiquitinated during infection." (PMID 40506485, 2025). "Genetic knockdown of SNAP29 inhibits virus replication and virion secretion at the early stage of infection." (PMID 38535609, 2024). "Studies showed that SNAP29 was involved in autophagy, synaptic transmission, cell division, and infection." (PMID 34659328, 2021). "This interaction between VP0 and SNAP29 opens the possibility for further investigation into its role in EV-A71 infection." (PMID 28677644, 2017). "Bacteria internalization as well as the location of the endogenous SNAP29 was determined 1 h post-infection." (PMID 23185475, 2012). "The activity of SNAP29 to prevent infection is also potentially relevant to bacterial pathogens." (PMID 31225470, 2018). "Also, infection with ΔS Legionella led to recruitment of SNAP29-GFP to intracellular bacteria." (PMID 40506485, 2025). "We further found that 2BC non-structural protein of EV-A71 specifically interacts with STX17 and SNAP29, and this reaffirms the importance of STX17 and SNAP29 in EV-A71 infection." (PMID 28677644, 2017). "To further characterize the involvement of SNAP29 in mast cell phagocytosis, we determined the kinetics of SNAP29 relocation in RBL-2H3 infected with E. coli at 1 h, 2.5 h, and 4 h post-infection." (PMID 23185475, 2012). "During infection, GPNMB mechanistically impairs xenophagy by binding to autophagosomal STX17, reducing its N296 site glycosylation, and promoting SNAP29 degradation, thereby preventing formation of the STX17-SNAP29-VAMP8 SNARE complex required for autophagosome-lysosome fusion." (PMID 41180454, 2025).
cancer (6 papers, 2009 to 2026). A tumor composed of atypical neoplastic, often pleomorphic cells that invade other tissues. "Thus, Snap29 might represent a novel safeguard to counteract the pathogenic processes involved in cancer." (PMID 36614195, 2023). "Among these SNARE proteins, SNAP29 depletion reduced exosome release in three other cancer cell lines, suggesting that SNAP29 plays a general role in exosome secretion." (PMID 38741166, 2024). "The expression of Cd52, Snap29, Mcoln1 and Nek6 genes, known to promote tumorigenesis in different cancer types, was up-regulated in peritoneal TCL1-Tg CLL cells." (PMID 38469292, 2024). "Inhibition of Snap29 enhances apoptosis and inhibits autophagy in cancer cells." (PMID 38469292, 2024). "The evidence demonstrates that the altered Snap29 activity might contribute to the pathogenesis of cancers." (PMID 36614195, 2023). "Importantly, the role of SNAP29 was also validated in three other cancer cell lines: MCF-7, MDA-MB-231 and Caco-2 cells, suggesting a more general role for SNAP29 in sEV secretion." (PMID 37285022, 2023). "Interestingly, the DEGs between Snap29+/+ and Snap29−/− ESCs were enriched in several cancer-related pathways." (PMID 36614195, 2023). "Importantly, depletion of SNAP29 also reduced the release of sEVs from three other cancer cell lines (MCF-7, MDA-MB-231 and Caco-2), indicating that SNAP29 may play a general role in sEV secretion." (PMID 37285022, 2023).
tumor (5 papers, 2016 to 2024). "SM15 also blocked SNARE complex formation by increasing O-GlcNAcylation of SNAP29, suggesting a key role for O-GlcNAcylation of SNAP29 in impeding autophagy flux and influencing tumor therapy." (PMID 39487556, 2024). "By analyzing the Human Protein Atlas, we compared the protein expression of SNAP23, SNAP25, SNAP29 and SNAP47 in ovarian normal and tumor tissues." (PMID 27855700, 2016). "Similar to the association pattern seen in TCGA survival data, in vivo tumorigenesis by KRAS-dependent human tumor cells in immune deficient mice required SNAP23 and VAMP3, but not SNAP29." (PMID 31712554, 2019).
bacterial infection (4 papers, 2012 to 2025). "Indeed, in mouse mast cells, an immune cell type specialized in clearing bacterial infections, Snap29 associates to E. coli containing phagosomes and its overexpression increases lysosomal clearance, suggesting that Snap29 assists antibacterial phagocytosis." (PMID 31225470, 2018). "Taken together, our data revealed that GPNMB blocked cellular autophagic flux by disrupting the interaction between STX17 and SNAP29 during bacterial infection." (PMID 40038549, 2025). "The Stx17–Snap29–Vamp8 complex also plays a crucial role in fish immune responses, with bacterial infection activating the STING pathway, which regulates the assembly of Stx17 with the Snap29–Vamp8 complex, thereby affecting autophagic flux and immune responses." (PMID 40076623, 2025). "Deglycosylation of GPNMB at residue N296 led to the degradation of SNAP29 upon bacterial infection." (PMID 40038549, 2025).
SNAP29 also shares sentences with these, for which no sentence is quoted: autism spectrum disorder (2 papers); enteroviral infections (2); nervous system disorder (2); palmoplantar keratoderma (2); Alzheimer disease (1); autosomal dominant nocturnal frontal lobe epilepsy (1); Bernard-Soulier syndrome (1); colorectal adenocarcinoma (1); depressive disorder (1); Failure to thrive (1); genetic diseases (1); hyperlipidemia (1); hypospadias (1); lung carcinoma (1); melanoma (1); morbid obesity (1); neurodegenerative disease (1); neurodevelopmental disorder (1); optic nerve hypoplasia (1); peripheral neuropathy (1); psychiatric disorder (1); Respiratory insufficiency (1); skin abnormalities (1); van den Ende-Gupta syndrome (1); Vici syndrome (1); viral diseases (1).